MEG3 (maternally expressed 3)
Diseases named in the same sentence as MEG3 in open-access papers (continued):
Sharing a sentence is not in itself a finding about the gene and the disease.
cancer (continued). "Comparative analysis confirmed that significant upregulation of Meg3 transcription in cancer cells of PDAC mouse models compared to normal epithelial cells." (PMID 34055623, 2021). "MEG3 can function as a competitive endogenous RNA, to mediate the key signalling proteins by which MEG3 coordinates a series of cellular processes protecting against cancer or metabolic disorders." (PMID 33332708, 2021). "This review focuses on the molecular mechanisms by which lncRNA MEG3 functions as a signal, scaffold, guide, and decoy for multi-lineage differentiation and even cancer progression." (PMID 34069546, 2021). "Their work demonstrates that MEG3 regulates the cancer stemness in liver cancer via the suppression of telomerase activity." (PMID 34069546, 2021). "We found significantly increased expression of MEG3 in the CAFs but little expression in cancer cells of the primary tumors, as well as remarkable transcript in cancer cells in metastatic PDAC tumors." (PMID 34055623, 2021). "By transcriptional profiling of these cells, a distinct metastatic cancer cell cluster was identified with specific MEG3 transcription, suggestion a different in vivo function of MEG3 in PDAC cancer cell metastasis with previous studies." (PMID 34055623, 2021). "In particular, we analyzed, by Droplet Digital PCR (ddPCR), six cancer-associated lncRNAs (MALAT1, NEAT1, HOTAIR, H19, PVT1, MEG3) in both FNAs and surgical tissues." (PMID 33030666, 2021). "In the following sections, we will review and highlight the characteristics and functions of some of the lncRNAs, i.e., HOTAIR, NEAT1, H19, MALAT1, and MEG3, frequently involved in several female-oriented cancers." (PMID 34885213, 2021). "In this review, we briefly summarized recent studies about the effect of MEG3 on the differentiation of embryonic and mesenchymal stem cells as well as the aggressiveness of cancer stem cells." (PMID 34069546, 2021). "There are several well-established lncRNAs that have been linked to cancers (e.g., HOTAIR, H19, MEG3, MALAT1)." (PMID 33803619, 2021). "In one interesting study on human cancer cells, expression of MEG3 modulated the expression of TGF-B pathway genes, and this was linked to the formation of RNA–DNA triplex structures across several of these target genes." (PMID 34338292, 2021). "Here, we provide an overview of the functional versatility of lncRNA MEG3 in modulating pluripotency, differentiation, and cancer stemness." (PMID 34069546, 2021). "Compared with adjacent tissues, LncRNA MEG3 in carcinoma tissues was evidently declined (P < 0.05), and miR-543 was evidently elevated (P < 0.05)." (PMID 34399782, 2021). "The experimental results revealed that LncRNA MEG3 was low in carcinoma tissues and peripheral blood, while miR-543 was high, suggesting that LncRNA MEG3 and miR-543 participate in the progression of NSCLC." (PMID 34399782, 2021). "To explore the roles of MEG3 and ZEB1-AS1 during cancer progress, we compared the expression values of MEG3 and ZEB1-AS1 in cancer samples and normal samples." (PMID 33101392, 2020). "Here, we defined an anti-cancer function of MEG3 through the regulation of EMT in aggressive EC cells." (PMID 33363153, 2020). "MEG3 is highly expressed in normal human tissue, but its expression is either decreased or abolished in many cancers, including GBM." (PMID 33066171, 2020). "Another study identified 126 lncRNAs including MEG3, ANRIL, and UCA1, which are closely implicated in cancer as putative targets of KSHV miRNA." (PMID 33519750, 2020). "The imprinted expression of these genes was related to cell development and growth, and experiments in vitro indicated MEG3 can suppress the proliferation of human cancer cells lines." (PMID 32669097, 2020).
cancer (continued). "Inactivation of the MEG3 gene in these cancers is partly attributed to promoter silencing by hypermethylation and contributes to cancer development." (PMID 32277605, 2020). "For example, the expression of MEG3 in cancer cells is significantly reduced and inhibits cell viability." (PMID 33256840, 2020). "Secondly, MEG3 plays a role in epigenetic regulation and can alter the function of cancer cells by affecting DNA methylation and regulating the functions of snoRNA and miRNA." (PMID 32669097, 2020). "MEG3 participates in carcinogenesis and cancer progression by regulating gene expression through chromatin modification, transcription, and posttranscriptional procession." (PMID 32219064, 2020). "Maternally expressed 3 (MEG3), a long chain noncoding RNA (lncRNA), has verified its function as a suppressor in several kinds of cancers." (PMID 32277605, 2020). "MEG3 is a lncRNA located on chromosome 14q32, which is closely related to the occurrence and development of cancer." (PMID 32277605, 2020). "Long noncoding RNA MEG3 (lncRNA MEG3) has been reported to function as a cancer suppressor gene in a variety of solid cancers." (PMID 32277605, 2020). "In line with this, expression of MEG3 from whole breast tissue is distorted as proportions of stroma vs epithelia in normal/cancer tissue are different, resulting in misleading interpretations." (PMID 32612992, 2020). "The clinical data showed that lncRNA MEG3 and E-cadherin expressions were both declined in carcinoma tissues as compared with their para-carcinoma tissues." (PMID 31938020, 2020). "Significant lower expression of MEG3 was confirmed in several types of cancers, such as gastric cancer, nonsmall cell lung cancer and gallbladder cancer." (PMID 31660855, 2019). "As with other studies, our work demonstrated that MEG3 represses cancer cells proliferation by inactivating Wnt signaling pathway." (PMID 31799068, 2019). "MEG3 overexpression in various types of human tumors and involvement in carcinogenesis and cancer progression have been reported." (PMID 31619233, 2019). "To date, accumulating evidence indicates that MEG3 plays a critical role in cancer progression and metastasis." (PMID 29449541, 2018). "Recent researches have demonstrated that MEG3 was involved in the tumorigenesis of diverse malignant tumors." (PMID 29808164, 2018). "The expression of MEG3 increased even at a pterostilbene concentration of 1 μM, possibly indicating a key role for MEG3 in the anti-cancer properties of pterostilbene." (PMID 30619763, 2018). "MEG3 downregulation was shown to play important roles in promoting malignant transformation, accelerating cancer progression, and reducing chemosensitivity." (PMID 30282996, 2018). "Invasiveness is a significant feature of cancer cells, and to examine the effect of MEG3 on invasion of GBC cells, we conducted transwell invasion assays." (PMID 30282996, 2018). "Maternally expressed gene 3 (MEG3) has been shown to be involved in a variety of cancers and is downregulated in most cancers and affects cell proliferation, progression, and prognosis." (PMID 29449541, 2018).
cancer (continued). "Maternally expressed gene 3 (MEG3) has been reported to play an important role in cancer initiation, metastasis, progression and chemo-resistance; we noted that MEG3 was highly overexpressed (FC=9.67) in EV71-infected skeletal muscle of mice." (PMID 30314355, 2018). "Among seven validated lncRNAs, there is already a considerable research and data for roles of HOTAIR and MEG3 in various cancer types." (PMID 29138748, 2017). "Meg3 was found to be expressed in cancers and function as negative regulators of growth, cancer inhibitors." (PMID 29383134, 2017). "Numerous studies have demonstrated that the expression level of maternally expressed gene 3 (MEG3) was lost in various cancers." (PMID 28157702, 2017). "Differential expression of MEG3 between normal and different grades of cancers offers the possibility of using MEG3 to assess the stage and prognosis of cancer." (PMID 29069869, 2017). "miR-26a and Meg3 were correlated with cancer progression, having prognostic value for patient stratification." (PMID 29206174, 2017). "Meg3 is among the most substantially underexpressed ncRNAs in cancer, leading to apoptosis arrest, cell cycle progression and almost unstoppable proliferation." (PMID 29206174, 2017). "We provide evidence that KSHV deregulates hundreds of host lncRNAs including many cancer-associated lncRNAs such as UCA1, ANRIL and MEG3 in both a miRNA dependent and independent manner." (PMID 28715488, 2017). "Recent studies demonstrated decreased MEG3 levels in a variety of primary human cancers and cancer derived cell lines." (PMID 29069869, 2017). "In this review, we summarized recent studies on MEG3 associated aberrant expression and its effects in cancers, and explored the potential of using MEG3 as biomarker for cancer diagnosis and prognosis." (PMID 29069869, 2017). "Well-designed studies related to specific cancer types and large sample sizes are needed to confirm the prognostic value of decreased lncRNA MEG3 in various cancers." (PMID 28157702, 2017). "It has been reported that expression of MEG3 RNA was detectable in many normal tissues, but lost or decreased in many primary cancers." (PMID 28415638, 2017). "The collected evidence demonstrated that MEG3 restricts cancer cells biological behavior by inhibiting their proliferation and inducing apoptosis." (PMID 29348851, 2017). "The alteration of MEG3 levels in various cancers suggested the possibility of using MEG3 level for cancer diagnosis and prognosis." (PMID 29069869, 2017). "We performed a meta-analysis to evaluate the relationship between the transcription levels of MEG3 and clinicopathological characteristics of patients with cancer." (PMID 28157702, 2017). "Long non-coding RNA (lncRNA) maternally expressed gene 3 (MEG3) has been demonstrated as an important regulator in diverse human cancers." (PMID 29238035, 2017). "Maternally expressed gene 3 (MEG3) is located at 14q32.2 and is involved in cancer development and metastasis." (PMID 28108736, 2017). "Among them the hypermethylation in the MEG3 promoter and IG-DMR regions probably play the most important role for the decrease of MEG3 expression in cancers." (PMID 29069869, 2017). "Modulating the levels of lncRNAs such as MEG3 through methods including over-expression, RNAi mediated gene silencing, or by small molecule inhibitors for cancer therapy looks promising in in vitro." (PMID 29069869, 2017). "Maternally expressed gene 3 (MEG3), a long non-coding RNA (lncRNA), is involved in cancer development and metastasis." (PMID 26934323, 2016). "Together, these data suggest that disruption of the pRb-DNMT1 pathway leads to a decrease in MEG3 expression, thereby contributing to the pro-proliferative state of certain cancer cells." (PMID 27832204, 2016).
cancer (continued). "Recent studies have demonstrated that lncRNA maternally expressed gene 3 (MEG3) is abnormal expressed in various human cancers, such as hepatocellular carcinoma, bladder cancer, glioma, and gastric cancer." (PMID 26934323, 2016). "Although, MEG3 is identified for the first time as an excellent indicator of BC prognosis, other studies have described the similar findings in several other cancers." (PMID 27793008, 2016). "In conclusion, the MS2 VLP-based lncRNA therapy strategy discussed here has many advantages, making it a promising vector for delivery of MEG3 on cancer therapy." (PMID 26992211, 2016). "Hypermethylation of both the MEG3 promoter and the IG-DMR have been shown to lead to loss of expression in human cancer cells." (PMID 27832204, 2016). "Here, we have shown that activation of pRb causes decreased expression of DNMT1, allowing for increased MEG3 expression and decreased cancer cell growth." (PMID 27832204, 2016). "In HCC, however, to date, only a few studies implicated lncRNAs, such as MALAT1, HOTAIR, HOTTIP/HOXA13, H19, HULC, MEG3, in the cancer pathogenesis." (PMID 25686840, 2015). "We observed that many genes related to various cancer types, primarily those associated with the nervous system, were deregulated in the MEG3-OFF hESCs in which MEG3 and the other downstream ncRNAs were repressed." (PMID 25559585, 2015). "A total of 9 CARs overlapped with annotated lncRNAs, of which NEAT1, MALAT1, and MEG3 are known to be regulated by cancer pathways." (PMID 25264628, 2014). "MEG3 suppresses cancer cell invasion and migration by inhibiting Rac1 expression via its 3′UTR." (PMID 41150811, 2025). "Whereas, ectopic expression of tumor suppressor lncRNA (MEG3) demonstrated anti-cancer effect." (PMID 39912983, 2025). "Through these interactions, MEG3 inhibits the proliferation and invasion of cancer cells." (PMID 41141357, 2025). "Finally, while MEG3-centered therapeutic strategies offer significant promise in cancer treatment, addressing the limitations related to delivery mechanisms and off-target effects is essential." (PMID 40242248, 2025). "For example, MEG3 (maternally expressed 3) functions as a suppressor in several types of cancers." (PMID 41020820, 2025). "MEG3 is a long noncoding RNA, and its role has been studied especially in cancer." (PMID 39684585, 2024). "MEG3 might act by modulating copper-related enzymatic pathways, potentially leading to copper accumulation in cancer cells and triggering cuproptosis." (PMID 39877157, 2024). "Additionally, MEG3 exerts its cancer-suppressive effect by downregulating the levels of miR-21-5p in CC cell lines." (PMID 38434620, 2024). "Maternally expressed gene 3 (MEG3), a long non-coding RNA derived from the DLK1-MEG3 locus at the chromosomal location 14q32.3, is well-established as a cancer-suppressive factor, which was initially recognized as the ortholog of gene trap locus 2 (Gtl2) in mice." (PMID 38434620, 2024). "Similar to IGF2 and H19, DLK1 and MEG3 also perform diverse biological functions in cancers." (PMID 38812777, 2024).
cancer (continued). "It is speculated that MEG3 regulates the proliferation, invasion, and migration of cancer cells through its binding to the GSK-3β protein." (PMID 36851033, 2023). "Several studies showed that MEG3 played various roles in different cancer types." (PMID 37525401, 2023). "MEG3 regulated cancer development by suppressing miRNAs in several types of cancer." (PMID 36851033, 2023). "MEG3 is downregulated in various cancer cell lines and primary human cancers." (PMID 36851033, 2023). "However, more investigations are needed to confirm the effect of DNC-induced MEG3 upregulation in the suppression of metastasis in this cancer." (PMID 36770654, 2023). "Aberrant expression of MEG3 has been shown in various cancers." (PMID 37525401, 2023). "MEG3 is a well-preserved long non-coding RNA (lncRNA) known for its anti-cancer properties." (PMID 38057891, 2023). "The purpose of this study was to elucidate whether the downregulation of MEG3 in OSCC cells is associated with H3K27me3 at MEG3 gene locus, and to uncover the transcription factors involved in the cancer‐suppressive function of MEG3." (PMID 36468944, 2023). "The downregulation of MEG3 was also observed in various cancer cell lines." (PMID 36851033, 2023). "Aberrant hypermethylation of the MEG3-DMR has been reported in various cancers." (PMID 37169950, 2023). "Additionally, MEG3 suppresses the metastatic progression of several cancers such as breast cancer, lung cancer, and HCC." (PMID 36770654, 2023). "Additionally, the unique MEG3 (ENST00000648820)-associated miRNA, hsa-miR-106a-5p, presented 38 enriched pathways and 39.5% of them are related to cancer." (PMID 38027526, 2023). "MEG3 inhibits cancer progression through different mechanisms." (PMID 36551518, 2022). "When analyzing the Receiver operating characteristic (ROC) curves for these genes we noted that, for the comparison of normal to cancer samples, MEG3 and MALAT1 had the highest Area Under the Curve (AUC), while when comparing normal vs. CIN, MLH1 and DAPK1 presented the highest AUC." (PMID 35682732, 2022). "Therefore, we generated an inducible MEG3 gene that contains elements for tagging RNA in living cells, to be expressed in a cancer cell line." (PMID 35741072, 2022). "Several studies reported that MEG3 can inhibit cancer cell proliferation in diverse cancers." (PMID 36033389, 2022). "MEG3 could enhance the sensitivity of cancer cells to chemotherapeutic agents by downregulating oncogenic miR-21-5p and upregulating its downstream target sex-determining region Y-box 7 (SOX7)." (PMID 35656022, 2022). "Therefore, we propose that MEG3 exerts anti‐cancer activity through negatively regulating EZH2 in NB cells." (PMID 35257481, 2022). "Furthermore, we highlighted the clinical significance of MEG3 as a biomarker for cancer prognosis, as well as a novel therapeutic strategy for cancer therapy." (PMID 36551518, 2022). "Research has also shown that MEG3 serves as a molecular sponge for miRNA to inhibit cancer as Zhu and Han (2019) found that lidocaine inhibits proliferation and promotes apoptosis of CC cells by modulating the MEG3/miR-421/anti-proligeration factor 1 (BTG1) axis." (PMID 36544907, 2022). "Based on the research basis of lncRNA MEG3 in cancer diseases, we boldly speculate that MEG3 will play a role in the emerging discipline of cancer heart disease." (PMID 36523500, 2022). "Another well-studied cancer-related imprinted lncRNA is MEG3, which acts as a cancer repressor." (PMID 34760887, 2021). "This is demonstrated by the sequential assembly of Prostate cancer associated non-coding RNA 1 (PRNCR1) and lncRNA prostate cancer gene expression marker 1 (PCGEM1) with the androgen receptor (AR), the MEG3 structure required for its tumor suppressive function." (PMID 34504983, 2021).